PLOD1 (procollagen-lysine,2-oxoglutarate 5-dioxygenase 1)
Diseases named in the same sentence as PLOD1 in open-access papers (continued):
Sharing a sentence is not in itself a finding about the gene and the disease.
glioma (continued). "Furthermore, to quantitatively predict the prognosis of glioma patients, we constructed a nomogram using grade, IDH mutation status, MGMT promoter methylation status, 1p19q codeletion status and PLOD1 expression level." (PMID 34040895, 2021). "Therefore, this study attempts to analyze the PLOD1 gene expression levels in glioma and normal tissue, using public database." (PMID 34040895, 2021). "The results showed that the expression level of PLOD1 was higher in glioma than normal tissues and high expression of PLOD1 was related to poor survival which can serve as an independent prognostic indicator for glioma patients." (PMID 34040895, 2021). "Moreover, previous research has presented that the expression PLOD1 can be predicted prognosis of IDHmut glioma patients, which involved in oxygen metabolism." (PMID 33503035, 2021). "Finally, we identified the PLOD1-related signaling pathways and suggested that PLOD1 acted as a cancer-promoting factor in tumor progression, providing a potential prognostic biomarker and therapeutic target for glioma patients." (PMID 34040895, 2021). "Therefore, PLOD1 may be a novel oncogene for glioma occurrence, progression, and MES transition in mesenchymal subtype GBM." (PMID 33420370, 2021). "We further performed rescue assays and found that NF-kB inhibitors treatment effectively inhibited glioma proliferation, invasion, migration, MES transition, and other malignant behaviors, resulting in the disappearance of all promoting effects caused by PLOD1 overexpression." (PMID 33420370, 2021). "Furthermore, targeting PLOD1 is most likely a potential therapeutic strategy for glioma patients." (PMID 34040895, 2021). "Co-expression of PLOD1 and COL6A2 results in poor prognosis in glioma." (PMID 36505882, 2022). "Thus, hypoxia due to rapid glioma growth can activate HIF-1, promoting the proliferation, invasion, and anti-apoptosis of GSCs through transcriptional regulation of PLOD1, leading to a series of malignant behaviors." (PMID 33420370, 2021). "Previous studies have revealed that PLOD2 and PLOD3 have predictive effects on the prognosis of glioma, we speculated that PLOD1 also influence the prognosis of glioma, although it has not been explored." (PMID 34040895, 2021).
bladder cancer (10 papers, 2019 to 2025). "PLOD1 was found to be directly regulated by miR-140-5p and abnormally expressed PLOD1 induced cancer aggressiveness in bladder cancer." (PMID 34646265, 2021). "Although PLOD1 was proven to promote aggressiveness of bladder cancer cells, the potential roles of PLOD1 and PLOD2 in RCC were not elucidated." (PMID 33287763, 2020). "Importantly, PLOD1 is aberrantly expressed and correlated with poorer outcome in bladder cancer, which is consistent with our finding." (PMID 34150627, 2021). "Compared with normal bladder samples, the protein expression of PLOD1, ATP6V1B1, HSD17B1, SERPINB7, and PYCR1 in bladder cancer tissues was upregulated, while EGR1 in cancer tissues was down-regulated." (PMID 37880682, 2023).
osteosarcoma (9 papers, 2020 to 2025). A usually aggressive malignant bone-forming mesenchymal neoplasm, predominantly affecting adolescents and young adults. "Elevated PLOD1 in osteosarcoma tissues is associated with distant metastasis, Enneking stage and a worse prognosis." (PMID 39767559, 2024). "Consistent with the results of GSE16091, only PLOD1 expression was associated with the prognosis of patients with osteosarcoma." (PMID 33134376, 2020). "Moreover, results of Cox regression analysis showed that a higher PLOD1 level was an independent risk factor of overall survival in patients with osteosarcoma." (PMID 33134376, 2020). "Moreover, PLOD1/2/3 were also reported to be associated with several other solid tumors, such as gastrointestinal carcinoma and glioma, while the expression and prognostic role of PLODs in osteosarcoma remain to be further illustrated." (PMID 33134376, 2020). "This is consistent with the previously reported role of PLOD1 in colorectal cancer, osteosarcoma and tongue squamous cell carcinoma." (PMID 39767559, 2024). "In the present study, we used bioinformatics and in-house cohort to analyze the differences in PLOD1/2/3 gene expression between osteosarcoma and normal tissue." (PMID 33134376, 2020). "In the present study, we found that PLOD1 was a potential biomarker in predicting the prognosis of osteosarcoma." (PMID 33134376, 2020). "In this study, we found that inhibition of PLOD1 expression in osteosarcoma cells dramatically reduced the expression of p-AKT and β-catenin, while no changes of total AKT expression were observed." (PMID 33134376, 2020). "PLOD1 was upregulated in osteosarcoma tissues compared with control tissues both in public datasets and in in-house cohort." (PMID 33134376, 2020). "Knocking down PLOD1 in osteosarcoma cells significantly decreased β-catenin reporter luciferase activity." (PMID 33134376, 2020). "Using RT0-PCR, we found that expression of PLOD1 significantly correlated with β-catenin expression in 56 osteosarcoma tissues (r = 0.67 and P < 0.01)." (PMID 33134376, 2020). "We found that PLOD1 was upregulated in osteosarcoma tissues when compared with normal bone tissues in GSE16088 and GSE33382, while the expression pattern of PLOD2 and PLOD3 was not consistent in two public datasets." (PMID 33134376, 2020). "Our results indicated that PLOD1 promoted proliferation, migration, and invasion of osteosarcoma cells." (PMID 33134376, 2020). "To determine vimentin expression after knocking down PLOD1 in osteosarcoma cells, we performed immunofluorescence (IF) staining, and the results also confirmed previous results using WB." (PMID 33134376, 2020). "Expression of PLOD1 in osteosarcoma tissues correlated with distance metastasis at diagnosis and advanced Enneking stage." (PMID 33134376, 2020). "Similar with our previous results, we found that only PLOD1 was higher in osteosarcoma tissues when compared with benign tumors." (PMID 33134376, 2020). "PLOD1 was also reported to be a prognostic biomarker for osteosarcoma." (PMID 38182978, 2024). "PLOD1 can promote cell migration and growth in osteosarcoma." (PMID 34131588, 2021). "Mechanistically, PLOD1 regulated β-catenin signaling pathway in osteosarcoma." (PMID 33134376, 2020). "Results of RT-PCR in 56 osteosarcoma tissues revealed that expression of PLOD1 was higher in patients with lung metastasis presented at diagnosis than those without metastasis (P < 0.01), while PLOD2 and PLOD3 expression presented no significance between two groups (all P > 0.05)." (PMID 33134376, 2020). "Taken together, our study indicated that PLOD1 might be involved in the malignancy process of osteosarcoma." (PMID 33134376, 2020). "PLOD1 was elevated in osteosarcoma and served as a prognostic biomarker." (PMID 33134376, 2020). "In this study, for the first time, we revealed that knockdown PLOD1 could inhibit proliferation, migration, and invasion of osteosarcoma cells." (PMID 33134376, 2020).
osteosarcoma (continued). "PLOD1 promoted proliferation, migration, and invasion of osteosarcoma cells by regulating the Wnt/β-catenin signaling pathway, which indicated PLOD1 might be a potential therapeutic target in osteosarcoma." (PMID 33134376, 2020). "PLOD1 was a novel prognostic marker, as well as a therapeutic target in osteosarcoma." (PMID 33134376, 2020). "This gave us a hint that PLOD1 might be a potential therapeutic target in osteosarcoma." (PMID 33134376, 2020). "Our above results indicated that PLOD1 was the only gene in the PLOD family, which might function in the malignancy processes of osteosarcoma." (PMID 33134376, 2020). "In our study, PLOD1 expression, not PLOD2 and PLOD3 expression, increased in osteosarcoma tissues compared with normal tissues." (PMID 33134376, 2020).
colorectal cancer (8 papers, 2019 to 2025). A primary or metastatic malignant neoplasm that affects the colon or rectum. "Previous studies showed that aberrant expression of PLOD1 was significantly associated with shorter survival in patients with gastric or colorectal cancer." (PMID 31199049, 2019). "Analysis of PLOD1 expression in 177 colorectal cancer tissues revealed that patients in the high-PLOD1 group had a reduced recurrence-free survival compared with those in the low-PLOD1 group." (PMID 33134376, 2020).
Kyphoscoliosis (7 papers, 2010 to 2025). An abnormal curvature of the spine in both a coronal (lateral) and sagittal (back-to-front) plane. "Kyphoscoliotic EDS (kEDS), associated with PLOD1 or FKBP14 gene mutations, presents with severe congenital hypotonia, progressive kyphoscoliosis, ocular fragility (e.g., scleral rupture), joint contractures, and, in some PLOD1 cases, hearing loss." (PMID 41245867, 2025). "Over 20 different mutations in the PLOD1 gene are responsible for Ehlers-Danlos Syndrome VIA (EDS VIA), which is the kyphoscoliosis type of this connective tissue disorder." (PMID 21176156, 2010). "Overall, Plod1–/– mice seem to only partially capture the human kEDS-PLOD1 phenotype with the presence of muscle hypotonia and aortic ruptures but without kyphoscoliosis or a clear skin phenotype." (PMID 34712265, 2021). "In view of the rapidly progressing kyphoscoliosis and ocular symptoms, mutation screening of PLOD1 was initially performed to exclude the kyphoscoliotic type of EDS (EDS, type VIA), but no PLOD1 mutation was identified." (PMID 21611149, 2011). "We recruited a Han Chinese neonate with PLOD1-related kEDS without kyphoscoliosis." (PMID 35252061, 2022). "Based on the results of 3 related individuals from consanguineous parents who shared the mutant PLOD1 genotype, but did not develop the same severity and age of onset of kyphoscoliosis, we conclude that this clinical feature might not correlate with the genotype." (PMID 21699693, 2011). "In addition, kyphoscoliosis represents a clinical feature of EDS type VIA with a high frequency of inter- and intrafamilial variability regarding severity and age of onset with no obvious association to the PLOD1 gene genotype." (PMID 21699693, 2011).
glioblastoma (6 papers, 2021 to 2025). The most malignant astrocytic tumor (WHO grade IV). "PLOD1 and PLOD2 were shown to be involved in hypoxia-induced metastasis and glioblastoma tumor progression." (PMID 36064320, 2022). "Evidence suggests that PLOD1 overexpression may contribute to increased invasiveness and the mesenchymal subtype (MES) of glioblastoma, indicating that PLOD1 could serve as a potential treatment target for mesenchymal glioblastoma, and possibly for all types of glioblastoma." (PMID 39664392, 2024).
hepatocellular carcinoma (6 papers, 2018 to 2025). A malignant tumor that arises from hepatocytes. "These evaluations demonstrated that PLOD1 is linked to HNSCC and the ncRNAs involved in WNT signaling in hepatocellular carcinoma, renal cell carcinoma, and various other signaling pathways." (PMID 36820030, 2023). "Furthermore, high expression level of PLOD1 was significantly correlated with the degree of response in hepatocellular carcinoma (HCC) patients and was positively correlated with immune infiltration." (PMID 35265665, 2021).
esophageal squamous cell carcinoma (5 papers, 2019 to 2024). Esophageal squamous cell carcinoma (ESCC) is a type of esophageal carcinoma (EC) that can affect any part of the esophagus, but is usually located in the upper or middle third. "In esophageal squamous cell carcinoma, the expression of tumor suppressor gene esophageal cancer-related gene 4 was negatively correlated with PLOD1 and PLOD2." (PMID 33420370, 2021). "For example, the high expression of PLOD1 and PLOD2 observed in esophageal squamous-cell carcinoma is negatively associated with expression of tumor suppressor gene." (PMID 31446433, 2019).
melanoma (5 papers, 2021 to 2024). A malignant, usually aggressive tumor composed of atypical, neoplastic melanocytes. "In fact, ACO1 and PLOD1 displayed LOF interactions in melanoma." (PMID 38640016, 2024).
dermatosparaxis (4 papers, 2012 to 2025). "Other types include kyphoscoliotic EDS (kEDS), which causes severe muscle weakness due to PLOD1 mutations, arthrochalasia EDS (aEDS) with extreme joint laxity resulting from COL1A1 or COL1A2 mutations, and dermatosparaxis EDS (dEDS) with fragile skin due to ADAMTS2 mutations." (PMID 40542421, 2025).
clear cell renal cell carcinoma (3 papers, 2020 to 2025). "A previous study assessed the expression and prognostic value of PLOD1/2/3 in wild-type and genetically mutated clear cell renal cell carcinoma (ccRCC) patients." (PMID 33134376, 2020). "For example, the PLOD1 mRNA and protein expression in clear cell renal carcinoma (ccRCC) tissues is significantly higher than that in normal tissues, which is also accompanied by a high pathological grade, advanced tumor staging and a poor OS." (PMID 39767559, 2024).
fibrosis (3 papers, 2014 to 2024). the formation of excess fibrous connective tissue in an organ or tissue in a reparative or reactive process. "Moreover, Masson trichrome and PSR staining showed excess adventitial collagen deposition in Ang II-treated Plod1-/- mice compared with Ang II-treated WT mice, indicating that LH1 deficiency promotes aortic fibrosis." (PMID 34646388, 2021). "In fibrosis, an increase in the expression of collagen-modifying enzymes such as prolyl hydroxylase (e.g. P4H1, P4HB) and lysyl hydroxylase (e.g. PLOD1 and -2) has been shown in e.g. lung and skin fibrosis." (PMID 24622053, 2014).
hearing loss (3 papers, 2020 to 2025). "Although patients with kEDS-FKBP14 present a clinically overlapping phenotype with PLOD1-related kEDS (kEDS-PLOD1), they can still be distinguished by normal LP/HP, presence of myopathy, and hearing impairment." (PMID 33129265, 2020). "Diagnostic differentiation criteria:PLOD1-associated kyphoscoliotic type 1 - marfanoid phenotype, profound skin bruisability, scleral and ocular ruptures;FKBP14-associated kyphoscoliotic type 2 - hearing loss, follicular hyperkeratosis, muscular atrophy, bladder diverticulum." (PMID 34504686, 2021).
aneurysm (2 papers, 2019 to 2021). Bulging or ballooning in an area of an artery secondary to arterial wall weakening. "This study aimed to evaluate the role of LH1 in aneurysm pathogenesis by using AAA specimens from patients and Ang II-induced dissecting AAA LH1-deficient (Plod1-/-) model mice." (PMID 34646388, 2021). "No aneurysm was observed in the saline-infused Plod1-/- mice, suggesting that LH1 deficiency did not result in dissecting AAA development under normal conditions." (PMID 34646388, 2021). "We sought to identify DEGs in PLOD1-kEDS and FKBP14-kEDS that are involved in modulating the vasculature, since rupture or aneurysm of medium-sized arteries have been described in both PLOD1-kEDS and FKBP14-kEDS and serves as a minor criteria in the diagnosis of kEDS." (PMID 31288483, 2019).
breast tumors (2 papers, 2023 to 2024). "In addition, they described that HIF-1α plays a critical role in collagen biogenesis in breast tumors by upregulating the expression of P4HA1, P4HA2, PLOD1, and PLOD2 hydroxylases as well as the lysyl oxidase family members LOX, LOXL2, and LOXL4." (PMID 37686617, 2023).
Ehlers-Danlos Syndrome type VI (2 papers, 2016 to 2019). "The under-hydroxylation of lysines at triple-helical domain cross-linking sites, and resulting inversed ratio of HP/LP cross-links in bone collagen closely resembles the collagen pathology in Ehlers-Danlos Syndrome type VI (EDS VI) caused by PLOD1 (encodes LH1) mutations." (PMID 27119146, 2016).
Hypertension (2 papers, 2020 to 2023). The presence of chronic increased pressure in the systemic arterial system. "In this way these authors could show that several genes impact hypertension and that multiple causative gene variants cosegregate at this locus; several linked genes thus control blood pressure (Agtrap, Clcn6, Mthfr, Nppa, Plod1)." (PMID 32741357, 2020).
keloid (2 papers, 2021 to 2022). An irregularly shaped, elevated mark on the skin caused by deposits of excessive amounts of collagen during wound healing. "Some modifying enzymes, which play important roles in the formation of collagen, were also shown to have high expression levels in keloids, including P3H3, P3H4, PLOD1, and CRTAP." (PMID 35435317, 2022). "The increased expression of PLOD1 and PLOD2 regulates the expression of 5-hydroxylysine in keloid tissue." (PMID 35222522, 2021).
Kyphoscoliotic EDS (2 papers, 2022 to 2025). "Kyphoscoliotic Ehlers Danlos Syndrome (kEDS) is a sub-type of EDS caused by autosomal recessive mutations in the PLOD1 gene which encodes the enzyme lysyl hydroxylase 1, or the FKBP14 gene which encodes the FK506 22 kDa binding protein." (PMID 36237549, 2022).
Kyphosis (2 papers, 2010 to 2015). Exaggerated anterior convexity of the thoracic vertebral column. "The QTL in the present study at SSC 5:72 and 73 Mb is near the association with marker 2928_3 (rs# 45434241), the QTL at SSC 6:60 Mb is only 5 Mb from PLOD1 which was associated with kyphosis in the linkage analysis and finally the QTL at SSC 6:105 Mb is near the microsatellite marker APR18." (PMID 26518887, 2015). "SNPs in KCNN2 on SSC2, RYR1 and PLOD1 on SSC6 and MYST4 on SSC14 were significantly associated with kyphosis in the resource population of swine (P ≤ 0.05)." (PMID 21176156, 2010).
lung carcinoma (2 papers, 2023 to 2024). "For example, decreasing PLOD1 expression impairs the proliferation and colony-formation capacity of A549 lung cancer cells by the activation of E2F transcription factor 1 (E2F1)." (PMID 39530057, 2024).
osteoporosis (2 papers, 2021 to 2023). A condition of reduced bone mass, with decreased cortical thickness and a decrease in the number and size of the trabeculae of cancellous bone (but normal chemical composition), resulting in increased fracture incidence. "In addition, target interaction network analysis by network-based visual analysis (miRNet) showed that five genes (GAPDH, PLOD1, LMNA, WDR1, and P4HB) with five miRNAs (hsa-let-7a/b-5p, hsa-let-7b-5p, hsa-mir-16-5p, hsa-mir-18a-5p, and hsa-mir-192-5p) were associated with osteoporosis by DisGeNET." (PMID 38132172, 2023).
renal carcinoma (2 papers, 2020 to 2022). A carcinoma arising from the epithelium of the renal parenchyma or the renal pelvis. "Moreover, three core glycolytic risk genes, CD44, PLOD1 and PLOD2, were capable of promoting the proliferation and invasion of renal cancer cells." (PMID 33287763, 2020). "MTT and Transwell assays revealed that silencing of CD44, PLOD1 and PLOD2 suppressed the proliferation and invasion of renal cancer cells." (PMID 33287763, 2020). "For example, the glycolysis process was found to be remarkably upregulated in RCC samples, and its core regulatory genes PLOD1, PLOD2, and CD44 could promote the proliferation of renal cancer cells." (PMID 35784919, 2022). "Therefore, we validated the biofunctions of CD44, PLOD1 and PLOD2 in renal cancer cells through further vitro experiments." (PMID 33287763, 2020).
adenoma (1 paper, 2024). A neoplasm arising from the epithelium. "Noteworthy, the numbers of RNA interactors of some MP-RNAs (WDR62, TGFBR3, RN7SL5P, RMRP, MIR663AHG, AJ009632.2, CDKL1, OPRD1, PLOD1, AL117692.1, ATP13A2, EPB41) in cancer tissue were significantly increased compared with that in paracancer and adenoma." (PMID 38773399, 2024).
adhesive capsulitis (1 paper, 2016). "In the present study, we quantified the mRNA expression of the TGFβ1, TGFβR1, LOX, PLOD1, PLOD2, COMP, FN1, TNC and TNXB genes in glenohumeral synovium/capsule samples collected from patients with adhesive capsulitis and from controls." (PMID 27438566, 2016).
bladder tumor (1 paper, 2024). "Finally, we assessed the effect of PLOD1 knockdown on bladder tumor cells using in vitro experiments." (PMID 39767559, 2024).